AR (androgen receptor)
Diseases named in the same sentence as AR in open-access papers (continued):
Sharing a sentence is not in itself a finding about the gene and the disease.
prostate adenocarcinoma (continued). "Notably, similar to our SPINK1 and AR IHC data in prostate adenocarcinoma patients, WCM12 also showed positive staining for SPINK1 and was negative for AR expression." (PMID 31959826, 2020). "Although it rarely arises de novo, NEPC may emerge from prostate adenocarcinoma (adeno-PCa) due to lineage plasticity induced by androgen receptor (AR)-targeted therapy." (PMID 30655535, 2019). "In line with this theory, we believe that during the evolution to hormone-independent, metastatic disease, prostate adenocarcinomas may therefore express progressively more AR-Vs." (PMID 30028845, 2018). "Our main objective was to identify the correlation between AR status and CgA level before the administration of anti-AR therapies and in different settings (chemotherapy-naïve and chemotherapy-treated patients) in prostate adenocarcinoma." (PMID 30337589, 2018). "Indeed, most cases of neuroendocrine prostate cancer, or anaplastic prostate cancer arise after hormone therapy and the evolution of an AR-neuroendocrine phenotype from prostate adenocarcinoma is a proposed mechanism of anti-androgen resistance." (PMID 25428917, 2015). "Prostatic adenocarcinomas are uniquely dependent on AR activity for growth and proliferation." (PMID 18007998, 2007). "Treatment-related neuroendocrine prostate cancer (NEPC) is an increasingly frequent mechanism of resistance to androgen receptor pathway inhibitor (ARPI) therapy in prostate adenocarcinoma (PRAD)." (PMID 41509338, 2025). "The majority of PCa is diagnosed as adenocarcinomas (i.e., prostate adenocarcinoma [PRAD]) expressing the androgen receptor (AR), with less than 1% as de novo neuroendocrine PCa (NEPC), which is AR–." (PMID 40231471, 2025). "While previous studies in prostate adenocarcinoma have shown that CCL5 upregulates androgen receptor signaling and contributes to enzalutamide resistance—an effect that may be mitigated by maraviroc—our current study focuses on the role of the unique context of cisplatin treatment in NEPC." (PMID 41152972, 2025). "Aberrant activation of androgen receptor (AR) signaling plays a crucial role in the progression of prostate adenocarcinoma (PRAD) and contributes significantly to the development of enzalutamide resistance." (PMID 38562999, 2024). "AR could essentially mediate the actions of BPA in advanced prostate adenocarcinomas." (PMID 37610061, 2023). "Prostate adenocarcinoma (PRAD) is primarily a hormone-driven disease mediated by cell growth that is driven by androgen receptor (AR) signaling." (PMID 35669435, 2022). "Given the predominance of older males, the major differential diagnostic consideration of primary and secondary sinonasal SDC is metastatic high-grade prostatic adenocarcinoma, as the two entities may share some morphological features and both express the androgen receptor." (PMID 33428064, 2021). "Prostate adenocarcinoma with focal increased neuroendocrine differentiation, confirmed by immunohistochemistry with neuroendocrine differentiation, but did not meet the criteria of group 3, of which 23 cases were matched, all 23 cases were AR positive, and 17 cases were PSA positive." (PMID 33598420, 2020). "Prostate adenocarcinoma with diffuse neuroendocrine differentiation (typical prostate acinar adenocarcinoma or prostate ductal adenocarcinoma with at least 1 neuroendocrine marker >50% positive), and of which 34 cases were matched, 27 cases were AR positive, and 23 cases were PSA positive." (PMID 33598420, 2020). "The TMPRSS2:ERG gene fusion (T:E fusion) puts ERG under the androgen receptor–regulated (AR-regulated) expression of TMPRSS2, and it is an early truncal alteration found in about half of prostate adenocarcinoma (PCa) cases in men of European ancestry." (PMID 41321318, 2025). "In NEPC tissues and compared to prostate adenocarcinoma, MUC1 was upregulated and negatively correlated with AR, which was suppressed." (PMID 40610411, 2025).
prostate adenocarcinoma (continued). "In line with this, gene correlation studies using datasets of prostate adenocarcinoma (PRAD) from TCGA in GEPIA revealed a positive correlation between H2AJ expression and each of the analyzed AR direct target genes." (PMID 40075640, 2025). "Previous studies suggest that most AR-independent NEPC emerges via lineage plasticity, in which selective pressures from intensive AR suppression drive histologic transformation from prostate adenocarcinoma to small-cell NEPC." (PMID 39859392, 2025). "Together, these data clearly demonstrate that TTP can reprogram AR signaling and induce PIN, a precursor lesion to primary prostate adenocarcinoma." (PMID 39560993, 2024). "Most PCa cases are characterized as prostatic adenocarcinoma (PAC) with luminal cell features and expression of AR and prostate-specific antigen (PSA)." (PMID 38515566, 2024). "The first two, SM0310 and CG0509, were derived from prostate adenocarcinomas of patients who failed both ADT and chemotherapy and displayed positive AR immunostaining." (PMID 38546787, 2024). "In contrast to prostate adenocarcinoma, a more common cancer, both SCNEC and LCNEC of the prostate lack significant PSA production and AR signaling." (PMID 39201018, 2024). "Prostate adenocarcinoma (PRAD), which expresses androgen receptor (AR), is the most frequent histological subtype of Pca (Chen, Chu & Lin, 2022)." (PMID 38562999, 2024). "SEMA3C expression is correlated with expression of steroidogenic enzymes CYP11A1 and SRD5A2 as well as the AR target gene, FKBP5, in prostate adenocarcinoma patients according to TCGA PanCancer dataset available on cBioPortal." (PMID 37800655, 2023). "Prostate adenocarcinoma is driven by androgens, expresses prostate-specific antigen (PSA) and other androgen receptor (AR) target genes, and responds to AR-directed therapies." (PMID 36317634, 2022). "AR directly represses transcription of the 4-O-sulfotransferase gene CHST11 under basal androgen conditions, maintaining steady-state CS in prostate adenocarcinomas." (PMID 35963852, 2022). "In prostate adenocarcinoma (PRAD), the top ranked factor is AR." (PMID 33778495, 2021). "IHC analyses showed positive staining for AR in tumor cells within sarcomatoid carcinoma lesions, indicating that they originated from prostatic epithelium and, perhaps, PIN and/or prostatic adenocarcinomas." (PMID 30677079, 2019). "Correlation analysis using The Cancer Genome Atlas (TCGA) prostate adenocarcinoma cohort data (n = 498) indicated that ING3 and AR mRNA levels were positively correlated." (PMID 28511652, 2017). "The co-expression of PHF8 with AR in clinical CRPC samples, normal mouse prostate, and adenocarcinomas of the prostate during PCa progression in a transgenic (TRAMP) mouse model supports the connection between PHF8 and AR." (PMID 27689328, 2016). "This discrepancy may arise from the fact that CDC25B overexpression can promote the AF2 domain of the AR to recruit CDC25B, thereby enhancing AR activation in prostate adenocarcinoma." (PMID 40216745, 2025). "Given that prostate adenocarcinoma is largely driven by androgens, it is not a surprise that several miRNAs modulate androgen receptor (AR) signaling." (PMID 39273446, 2024). "Across all targets studied here, the expression in AR + /NE+ tumors mostly resembled AR + /NE- tumors, highlighting that this subtype exhibits predominantly luminal prostatic adenocarcinoma molecular features and not those of NEPC." (PMID 38760413, 2024).
prostate adenocarcinoma (continued). "Development of HGPIN and prostatic adenocarcinoma lesions in Osr1-Cre-driven hARtg transgenic mice but not in previous AR transgenic models regulated by the PB promoter implicates the critical role of prostatic Osr1-lineage cells in prostate tumorigenesis." (PMID 35902588, 2022). "Cell growth of AVPC often occurs completely independent of the androgen receptor signal transduction pathway and cells have mostly lost the typical cellular features of prostate adenocarcinoma." (PMID 35109899, 2022). "The androgen receptor (AR) drives MPC2 transcription and increases pyruvate oxidation and lipogenesis, which seems to be important for the progression of castration-resistant AR+ prostate adenocarcinoma subtypes." (PMID 33804985, 2021). "Neuroendocrine prostate cancer (NEPC) is an androgen receptor-negative prostate cancer subtype that can occur sporadically but most commonly evolves from primary prostate adenocarcinoma." (PMID 27015368, 2016). "PC-3 and DU-145 cells were androgen receptor (AR)-negative PCa cells established from human prostatic adenocarcinoma metastatic to bone and brain, respectively." (PMID 26318033, 2015). "Although LCNEC may express PSA or AR to some extent, the levels are typically absent or lower than those found in high-grade prostate adenocarcinoma, helping differential diagnosis." (PMID 39201018, 2024). "NK1R was highly expressed in NE-like cell lines PC-3 and DU145, both positive of NE markers (CgA and ENO2) and negative of AR/PSA; in contrast, in AR-positive prostate adenocarcinoma cell line LNCaP and 22Rv1, NK1R expression is much lower and NE markers are marginal." (PMID 37385990, 2023). "While some have postulated that BAT may reverse transdifferentiation of prostate adenocarcinoma to neuroendocrine prostate cancer, which can occur as a mechanism of resistance to AR-axis inhibitors, we did not assess this possibility in the current study." (PMID 36194476, 2022). "In prostate adenocarcinoma (PRAD), KDM3A functions as a transcriptional coactivator for the androgen receptor (AR; Gene ID: 367)." (PMID 28416760, 2017). "A major challenge in the forthcoming years could consist in the efficient management of neuroendocrine-differentiated prostate adenocarcinoma, most often appearing secondary to treatment with AR inhibitors and displaying decreased or no expression of AR and PSMA." (PMID 37370743, 2023). "In prostate adenocarcinoma, this non-canonical function of EZH2 can collaborate with the AR transcriptional machinery to drive AR-signaling or with N-myc to modulate plasticity." (PMID 38405800, 2024). "This approach allows for the classification of tumors into four clinically relevant subtypes: prostatic adenocarcinoma (AR+/NE−), NEPC (AR−/NE+), amphicrine carcinoma (AR+/NE+) and double negative CRPC (AR−/NE−) 20,37." (PMID 38196594, 2023). "In AR-negative NEPC cells, enzymatic EZH2 inhibitors are substantially more effective than their counterparts since their actions in AR function in prostate adenocarcinoma are independent of their catalytic activity." (PMID 36678591, 2023). "Performing a co-culture of neutrophils and cancer cells, we next examined neutrophil killing of AR-negative PAIII cells, a rat prostate adenocarcinoma cell line which is bone metastatic in vivo." (PMID 35604506, 2022).
prostate adenocarcinoma (continued). "We found that the AR-negative PC3 and NE-like NCI-H660 and LASCPC01 cell lines expressed higher PKLR and NE markers and lower androgen-responsive markers than did the AR-positive VCaP, LNCaP, and C4-2 prostate adenocarcinoma cell lines." (PMID 35306527, 2022). "Gene correlation study by using datasets of prostate adenocarcinoma (PRAD) from TCGA and of normal prostate samples from GTEx (Genotype-Tissue Expression) from GEPIA for LYL1 and each of the analyzed known AR direct target genes revealed a negative correlation with the LYL1 expression." (PMID 39668349, 2024). "Moreover, ADT was shown to be a key driver of the neuroendocrine differentiation of the prostate adenocarcinoma to NEPC, and so it is not surprising that the incidence of treatment-induced NEPC is rising because of the widespread use of more potent androgen receptor (AR) pathway inhibitors." (PMID 32531951, 2020).
metastatic disease (176 papers, 2002 to 2025). "There is now evidence that targeting the AR causes cancer cells to secrete IL-1β, an inflammatory molecule with a recognized role in promoting the growth and survival of cancer cells in metastatic tumors." (PMID 39858071, 2025). "Transcription factor 19 (TCF19) stood out as an unprecedented epithelial gene upregulated in metastatic disease, with prognostic potential and negatively associated with the activity of the androgen receptor." (PMID 40952912, 2025). "They reported that CTCs with high AR protein expression are linked to the course of metastatic disease and AR-V7 expression in CTCs predicts a higher response to second-generation antiandrogen therapy." (PMID 40026568, 2024). "To examine the association of valine catabolism in advanced and metastatic disease, we interrogated a microarray (RNA) dataset generated from long-term (21-day) treatment of PCa cells with the AR antagonist, enzalutamide." (PMID 39025852, 2024). "In 1% of primary PC cases, mutations and amplifications of the AR are observed, with this rate increasing to approximately 60% in metastatic tumors." (PMID 38750579, 2024). "Neuroendocrine differentiation (NED) is a hallmark of aggressive, AR-independent and treatment-resistant PCa, and can occur in both primary and metastatic disease." (PMID 37740039, 2023). "Among men with metastatic disease, expression of genes proximal to AR sites gained in metastatic tumors was associated with clinical outcome." (PMID 35509021, 2022). "Among men with metastatic disease, expression of genes proximal to AR sites gained in metastatic tumors was associated with clinical outcomes." (PMID 35509021, 2022). "Compared to primary PCa, mCRPC tumors showed higher overall burden in copy number variations and point mutations in the PI3K pathway, but also more frequent amplification and/or mutation of AR signaling in metastatic tumors." (PMID 32878288, 2020). "Loss of AR correlated with higher grade tumors [S55]; on the other hand, AR positivity was more frequent (71%) in metastatic disease than in primary tumors [S54]." (PMID 25595907, 2015). "Of the many APUC genes that have been associated with the activation of AR, we found that 6 (HSD3B1, HSD3B2, CYP11A1, CYP11B1, CYP17A1, and CYP3A43) exhibit robust association in prostate and metastatic tumors and were mutually exclusive with heightened AR activity." (PMID 39207857, 2024). "nmCRPC patients with a high risk of progression to metastatic disease who are identified by a prostate-specific antigen doubling time (PSADT) ≤10 months are eligible for treatment with the novel androgen receptor inhibitors (ARIs), shown to delay disease progression and extend survival." (PMID 38322282, 2023). "Of note, Black men, who have the highest rates of PC incidence and mortality, were more likely to have metastatic tumour mutations in the AR and DNA-repair genes, as well as actionable genetic mutations, than either White or Asian patients with metastatic disease." (PMID 35053569, 2022). "Similarly, although a significant increase in Ki67 in the epithelium associated with AR is present in metastatic disease, stromal Ki67 significantly decreased in TNM4." (PMID 33920263, 2021). "Interestingly, AR signaling was more frequently altered in the metastatic tumors, by amplification or mutation of AR, events that are usually absent in primary tumors, indicating that most mCRPC tumors have active AR signaling pathway." (PMID 29690565, 2018). "Separately in this cohort, high CDK2AP1 and high AR expression were significantly associated with metastatic disease (p value 0.034 and 0.019, respectively) and when combined, there is a higher rate of metastatic disease observed in high CDK2AP1 and high AR expression cases (p value 0.013)." (PMID 36362115, 2022). "Thus, DNAH8 is a new regulator of AR associated with metastatic tumors and poor prognosis." (PMID 27363033, 2016).